MR1 (major histocompatibility complex, class I-related)
Diseases named in the same sentence as MR1 in open-access papers (continued):
Sharing a sentence is not in itself a finding about the gene and the disease.
lupus (5 papers, 2015 to 2022). "In a spontaneous lupus mouse model, germinal center reactions, plasma cells and T follicular helper (Tfh) cells were reduced in MR1−/− deficient mice compared to their littermate counterpart." (PMID 35562666, 2022). "MR1 deficiency influenced autoantibody production and the disease severity of lupus in FcγRIIb−/−Yaa mice, suggesting that MAIT cells are responsible for enhanced autoimmune responses in lupus." (PMID 31849932, 2019). "We speculate that the difference in the effects between MR1 deficiency and i6-FP treatment on the disease course of lupus may be due to the double-sided functions of MAIT cells on autoimmune responses." (PMID 31849932, 2019). "Using two approaches to obtain MAIT cell deficiency, MR1 knockout animals and use of an inhibitory MR1 ligand, we demonstrate that MAIT cells augment the disease course of lupus by enhancing autoantibody production and tissue inflammation." (PMID 31849932, 2019). "Thus, MR1 deficiency had little effect on anti-dsDNA antibody levels for the first 3 months of age, and the inhibition of MAIT cell activation with i6-FP treatment had beneficial effects on the disease course of lupus." (PMID 31849932, 2019). "As MR1-restricted antigens are vitamin B metabolites originating from biosynthetic pathways present in various types of microbes, including indigenous bacteria, lupus monocytes may be exposed to such antigens and subsequently induce activation of MAIT cells." (PMID 28288675, 2017). "Therapeutic efficacy has been demonstrated previously with the full-length MR1 anti-CD40L antibody, but the data presented here suggest that CDP7657, lacking any Fc-function, may have the potential to be an effective therapy in lupus patients with demonstrable disease." (PMID 26335795, 2015).
Arthritis (4 papers, 2018 to 2020). Inflammation of a joint. "We previously reported that MR1 deficiency exacerbated EAE, but inflammatory responses were reduced in arthritis models using MR1-deficient mice." (PMID 31849932, 2019). "An effector role for MAIT cells in arthritis was demonstrated in MR1-deficient mice, after both CIA and CAIA disease induction." (PMID 30008717, 2018). "Thus, MAIT cells promote inflammation and exacerbate the disease in murine models of arthritis while mice with MR1 deficiency develop a less severe disease compared to control." (PMID 32849648, 2020). "Our group demonstrated that MAIT cells exacerbated joint inflammation in arthritis models, and MAIT cells exerted their effector function even when they were adoptively transferred into MR1-deficient mice." (PMID 29942318, 2018). "MR1 deficiency significantly reduced arthritis and adoptive transfer of MAIT cells to MR1−/− mice exacerbated arthritis in CAIA." (PMID 30008717, 2018). "Because MR1 deficiency had little effect on T and B cell responses against CII, MAIT cells appeared to contribute to the effector phase of arthritis." (PMID 29942318, 2018).
colitis (4 papers, 2023 to 2025). Inflammation of the colon. "A recent study by Yasutomi and colleagues highlighted the pathogenic role of MAIT cells in IBD, showing that MR1 deficient mice have a less severe outcome in an Oxazolone-induced colitis model." (PMID 40977727, 2025). "Interestingly, the authors also reported that the administration of the MR1 antagonist, isobutyl 6-formyl pterin reduced the colitis severity in the same model as well as decreased the production of cytokines by MAIT cells." (PMID 40977727, 2025). "In oxazolone colitis, a murine model of UC which histologically resembles UC and is predominantly mediated by type-2 cytokines, it has been proposed that MAIT cell play a directly pathogenic role as disease severity is reduced in MR1-/- animals or with MR-1 antagonist isobutyl 6-formyl pterin." (PMID 36911683, 2023). "Additionally, in an oxazolone-induced mouse model of colitis, inhibiting MAIT cell activation through MR1 knockout or administration of the MR1 antagonist isobutyl 6-formylpterin has been shown to mitigate the severity of UC." (PMID 40025566, 2025). "In the azoxymethane (AOM)/DSS model of colitis-induced colorectal cancer, rectal tumor development is enhanced in mice lacking MAIT cells as compared with Mr1+ cage mates, further emphasizing the anti-inflammatory role of MAIT cells upon DSS treatment." (PMID 39446132, 2025).
liver diseases (4 papers, 2016 to 2025). "MR1 expression is inducible by inflammation and appears increased on liver epithelia and myeloid cells in several liver diseases." (PMID 41511352, 2025). "A recent report about the ability of acetyl-6-formylpterin (acetyl-6-FP, an MR-1 antagonist) to accelerate regression of liver fibrosis in mice supports the concept of using inactive MR1 ligands in the treatment of liver diseases." (PMID 35641678, 2022). "CD40L upregulation was mediated both by E. coli presented by MR1 as well as IL-12 and IL-18, providing a mechanism through which MAIT cells could drive bile duct damage in inflammatory liver disease in the absence of infection, in a non-specific manner." (PMID 26743076, 2016).
liver fibrosis (4 papers, 2020 to 2023). "Importantly, we also unravel that acceleration of liver fibrosis regression is promoted by blocking MR1 presentation by either Ac-6-FP or an MR1 antibody." (PMID 37005415, 2023). "WT, Mr1+/+ B6-MAITCAST and Mr1-/- B6-MAITCAST animals were placed on an SSD and liver fibrosis was determined after 16 weeks." (PMID 37774007, 2023).
meningeal TB (4 papers, 2017 to 2020). "Of note, a MR1 gene polymorphism, associated with lower MR1 expression, was recently associated with susceptibility to meningeal tuberculosis in Vietnamese adult patients." (PMID 30853958, 2019). "As recently shown, a polymorphism in the human MR1 gene, associated with MR1 expression, is associated with susceptibility to meningeal TB in Vietnamese adult patients." (PMID 29326714, 2017). "In humans, MR1 polymorphisms are associated with susceptibility to TB meningitis." (PMID 33042140, 2020).
acute myeloid leukemia (3 papers, 2025). Acute myeloid leukemia (AML) is a group of neoplasms arising from precursor cells committed to the myeloid cell-line differentiation. "Potent stimulation of MR1-restricted T cellsMR1-M3Ade tetramer reactive T cells were found in acute myeloid leukemia, cell lung adenocarcinoma, and hepatocarcinoma." (PMID 40746558, 2025). "Here, we searched for cancer-activated, MR1-restricted T cell populations in 10 healthy donors and a patient with acute myeloid leukemia (AML)." (PMID 39744940, 2025). "MAIT cells possess MR1‐restricted tumor recognition ability; for instance, acute myeloid leukemia (AML) cells highly express MR1, making them a new target for chimeric antigen receptor (CAR)–MAIT therapy—preclinical models have shown that the tumor clearance rate can reach 60%." (PMID 41179703, 2025).
E. coli infection (3 papers, 2022 to 2025). "MR1‐deficient mice (which lack MAIT cells) exhibit increased splenic bacterial loads after E. coli infection, enhanced susceptibility to K. pneumoniae, and high mortality owing to disseminated infection." (PMID 41179703, 2025). "Fragments of the detected ion at m/z 428.1197 ([M-H]-) from recombinant MR1 expressed in insect cells with M. smegmatis (mc2155) or E. coli infection match the fragmentation pattern of synthetic compounds with unclear accuracy." (PMID 40746558, 2025). "Temporal dynamic studies have shown that during E. coli infection, early activation is primarily MR1 dependent, whereas late‐stage activation requires the combination of signals from MR1 and IL‐12/IL‐18." (PMID 41179703, 2025).
fungal infections (3 papers, 2019 to 2025). "While their response to bacterial and fungal infections depends on the recognition of MR1 presentation of riboflavin pathway-derived antigens, MAIT cell responses to viral agents are independent of MR1-Ag." (PMID 36189274, 2022).
lung adenocarcinoma (3 papers, 2017 to 2024). A carcinoma that arises from the lung and is characterized by the presence of malignant glandular epithelial cells. "To investigate the role of MR‐1 in NSCLC, we compared the most common subtype of NSCLC, lung adenocarcinoma (LUAD), in the TCGA database." (PMID 38342606, 2024). "We found positive correlations between MR1 expression and MAIT scores in CRC (p = 0.0081, Pearson correlation), stomach adenocarcinoma (p = 0.0015), prostate adenocarcinoma (p = 1.29e−10), lung adenocarcinoma (p = 0.00088), and clear cell renal cell carcinoma (p = 0.013)." (PMID 32849590, 2020).
multiple myeloma (3 papers, 2018 to 2024). "Beyond solid tumors, MR1 expression is also observed in multiple myeloma cell lines, which can present the vitamin-B derivative ligand to MAIT cells, which in turn can induce cytotoxic activity towards these myeloma cells." (PMID 38545100, 2024). "It was next important to examine whether MR1+ myeloma cells could be targeted by MAIT cells." (PMID 29515123, 2018).
Obesity (3 papers, 2020 to 2023). Accumulation of substantial excess body fat. "In contrast, MAIT cells in obesity induced M1 polarization of macrophages in an MR1-dependent manner, thereby promoting inflammation with high TNF production and metabolic dysfunction." (PMID 36875139, 2023). "To determine the role of MAIT cells in the pathogenesis of T2D and obesity, we analyzed MR1−/− B6 mice that lack MAIT cells, since the MR1 molecule is required for thymic development of MAIT cells." (PMID 32709874, 2020). "The expansion and maturation of MAIT cells require the gut microbiota and antigen‐presenting molecule MR1, suggesting that MAIT cells may play a unique role in bridging gut microbiota, obesity, and obesity‐associated inflammation." (PMID 33332759, 2021). "Decreased bacterial-derived agonist ligand availability might represent a way to dampen MAIT cell activation in inflammatory conditions, since our data showed that MAIT cell activation in vitro and in vivo in the context of obesity is MR1-dependant." (PMID 32709874, 2020).
primary immunodeficiency (3 papers, 2023 to 2024). "MR1 has significantly associated with “B cell receptor signalling pathway”, “Primary immunodeficiency”, “Viral carcinogenesis”, “Colorectal cancer”, and “Th1 and Th2 cell differentiation”." (PMID 37587523, 2023). "For instance, a patient with a homologous MR1 mutation at position 31 Arg to His substitution (position 9 in mature MR1 protein: MR1R9H/MR1R9H) was discovered to display primary immunodeficiency due to functional MR1 deficiency, with no circulating MAIT cells." (PMID 37409131, 2023).
respiratory infections (3 papers, 2015 to 2025). "Studies performed in MR1-deficient mice suggest that MAIT cells can provide anti-bacterial control within the first few days post-infection, as well as contribute to enhanced adaptive immunity in murine models of respiratory infections." (PMID 26217338, 2015). "Cigarette smoke is a diverse mix of chemicals that bind the antigen-presenting protein MR1 and modulate MAIT cell function in the lung through diverse mechanisms, impacting their ability to respond to respiratory infections and potentially contributing to disease." (PMID 39820322, 2025).
tuberculosis (3 papers, 2010 to 2022). A chronic, recurrent infection caused by the bacterium Mycobacterium tuberculosis. "Direct ex vivo analysis demonstrates that Mtb-reactive MAIT cells are decreased in peripheral blood mononuclear cells (PBMCs) from individuals with active tuberculosis, are enriched in human lung, and respond to Mtb-infected MR1-expressing lung epithelial cells." (PMID 20613858, 2010). "Mucosal-associated invariant T (MAIT) cells are MHC-related protein 1 (MR1)–restricted T cells, which are reactive against M. tuberculosis, and underexplored as potential TB vaccine targets." (PMID 31611259, 2019).
cervical carcinoma (2 papers, 2018 to 2021). A carcinoma arising from either the exocervical squamous epithelium or the endocervical glandular epithelium. "MR1 expression for cervical cancer was not significant in cancerous or non-cancerous tissue (P = .2054)." (PMID 33948562, 2021).
Chorea (2 papers, 2013 to 2020). Chorea (Greek for 'dance') refers to widespread arrhythmic involuntary movements of a forcible, jerky and restless fashion. "PnKD is commonly caused by mutations in the myofibrillogenesis factor 1 gene (MR1), resulting in episodic bouts of involuntary moments such as chorea, dystonia, and ataxia that are triggered by caffeine, fatigue, alcohol, stress, intense emotions, and laughter." (PMID 32775036, 2020).
colon tumor (2 papers, 2019 to 2025). "In addition, MR1 is expressed in colon tumor tissue and there would thus be ample possibilities for local presentation of microbial antigens to tumor-infiltrating MAIT cells." (PMID 31073372, 2019). "Of note, the growth of the colon tumor cell line MC38 is similar in Mr1+ and Mr1−/− mice upon intrarectal transplantation, arguing against a direct antitumor effect of MAIT cells in the colon." (PMID 39446132, 2025).
colorectal cancer (2 papers, 2020 to 2023). A primary or metastatic malignant neoplasm that affects the colon or rectum. "Finally, in colorectal carcinoma and four other cancer types, we found a positive correlation between MR1 expression and estimated MAIT cell abundance." (PMID 32849590, 2020).
diabetes (2 papers, 2020 to 2021). "We first explored whether anti‐CD45RB or/and MR-1 therapy could prolong the survival of allografts from recipient C57 mice with STZ-induced diabetes." (PMID 33270650, 2020).
glioblastoma (2 papers, 2016 to 2025). The most malignant astrocytic tumor (WHO grade IV). "MR1(Fv)-PE38 was effective at killing glioblastoma cells both in vitro and in vivo." (PMID 27153091, 2016). "The scFv MR1 was isolated from this screen and was fused to the PE38 exotoxin to create MR1(Fv)-PE38 for treatment of glioblastoma expressing EGFRvIII." (PMID 27153091, 2016).
graft versus host disease (2 papers, 2020 to 2023). An immune system disorder that occurs after allogeneic hematopoietic stem cell transplant and is a reaction of donor immune cells against host tissues. "MAIT cell-deficient mice Mr1–/– that received allogeneic bone marrow transplantation develop more severe graft-versus-host disease (GVHD) than normal mice." (PMID 33185693, 2020).
inflammatory bowel disease (2 papers, 2025). A spectrum of small and large bowel inflammatory diseases of unknown etiology. "MAIT cells actively participate in the occurrence and development of inflammatory bowel disease (IBD) by virtue of their MR1‐restricted antigen‐recognition ability and tissue‐homing properties." (PMID 41179703, 2025).
influenza (2 papers, 2018 to 2022). An acute viral infection of the respiratory tract, occurring in isolated cases, in epidemics, or in pandemics; it is caused by serologically different strains of viruses (influenzaviruses) designated A, B, and C, has a 3-day incubation period, and usually lasts for 3 to 10 days. "Riboflavin synthesis is broadly conserved, but the roles or mechanisms of riboflavin in MR1–/– mouse influenza infection are not well understood." (PMID 35722312, 2022). "MAIT cell-deficient MR1−/− mice show enhanced weight loss and mortality to severe (H1N1) influenza." (PMID 30413689, 2018).
Legionella infection (2 papers, 2018 to 2019). "Initially, we examined the impact of Legionella infection on MAIT cells (defined as CD45+TCRβ+ MR1-5-OP-RU tetramer-positive cells) in vivo in a murine model using intranasal (i.n.)infection with live L. longbeachae in immunocompetent mice." (PMID 30135490, 2018).
meningeal disease (2 papers, 2020 to 2022). "In humans, the importance of MR1 in the control of Mtb was suggested in a study showing that an MR1 single-nucleotide polymorphism was associated with Mtb meningitis." (PMID 36430890, 2022). "MR1-KO mice, which lack MAITs, show a reduced ability to control initial infection, and polymorphism associated with reduced MR1 expression in humans is linked to TB susceptibility and meningeal disease." (PMID 31763997, 2020).
paroxysmal non-kinesigenic dyskinesia (2 papers, 2021 to 2025). "The PNKD gene, also known as MR-1 (Myofibrillogenesis Regulator 1), is associated with paroxysmal non-kinesigenic dyskinesia (PNKD)." (PMID 40958306, 2025). "Dyskinesia in PKD seems to be mechanistically distinct from paroxysmal non-kinesigenic dyskinesia (PNKD), which is caused by dominant mutations in MR-1, and is associated with alterations in dopaminergic signaling in the striatum." (PMID 34101060, 2021).
pneumonia (2 papers, 2018 to 2019). An acute, acute and chronic, or chronic inflammation focally or diffusely affecting the lung parenchyma, caused by an infection in one or both of the lungs (by bacteria, viruses, fungi, or mycoplasma.). "This might imply a minimal role for MAIT cells during S. pneumoniae-induced pneumonia in humans although this observation should be confirmed by the use of MR1 tetramers." (PMID 30116242, 2018). "To better understand the relationship between MR1/5-OP-RU tetramer staining, CDR3α usage and MR1-dependent T cell activity, we sorted MR1/5-OP-RU positive cells from the BAL of an available individual with non-TB pneumonia and performed limiting dilution cloning using anti-CD3 and IL-2 stimulation." (PMID 31231693, 2019). "However, the precise functions of MAIT cells in pneumococcus-induced pneumonia are currently unknown since data from either Mr1−/− or Vα19iTgCα−/−Mr1−/− mice are not yet available." (PMID 30116242, 2018).
prostate carcinoma (2 papers, 2020 to 2021). A carcinoma that arises from epithelial cells of the prostate gland. "Moreover, in an analysis of public datasets, gene expression signatures associated with MAIT-cells were identified in prostate cancer, correlated with MR-1 expression, and were associated with a favorable prognosis." (PMID 34737749, 2021). "Interestingly, in kidney, urothelial, and prostate cancers, the high MR1 mRNA expression level is associated with better probability of survival than those with low levels of MR1 mRNA expression." (PMID 32756356, 2020). "We find that a potent MAIT-cell agonist can elicit MR-1-dependent lysis of a prostate cancer cell line, and that this is enhanced by PD-1 blockade." (PMID 34737749, 2021). "We find that this MAIT-cell dysfunction is associated with enhanced PD-1 expression upon stimulation, and that the combination of a potent MR-1 ligand with PD-1 blockade enhances MR-1-dependent cytotoxicity against a prostate cancer cell line." (PMID 34737749, 2021). "Finally, we report that 5-A-RU elicits MR-1-dependent lysis of a prostate cancer cell line by human PBMCs in vitro, and that this effect is enhanced by pembrolizumab, in association with increased MAIT-cell expression of the cytotoxicity-associated molecules CD107a and IFN-γ." (PMID 34737749, 2021).
psoriasis (2 papers, 2020 to 2023). An autoimmune condition characterized by red, well-delineated plaques with silvery scales that are usually on the extensor surfaces and scalp. "Despite these shortcomings, our data shed light on hitherto unexplored parts of the TCR repertoire of MR1-restricted MAIT cells in psoriasis, revealing their extremely diverse, individually unique repertoire, which significantly expands with age." (PMID 38017021, 2023).